BRAF (B-Raf proto-oncogene, serine/threonine kinase)
Diseases named in the same sentence as BRAF in open-access papers (continued):
Sharing a sentence is not in itself a finding about the gene and the disease.
Alzheimer disease (5 papers, 2021 to 2024). A progressive, neurodegenerative disease characterized by loss of function and death of nerve cells in several areas of the brain leading to loss of cognitive function such as memory and language. "Additionally, a drug used in Alzheimer's disease can bind to RAF1 and BRAF interface." (PMID 38216592, 2024).
autoimmune (5 papers, 2014 to 2024). "Furthermore, they can also derive from immune-mediated antitumor mechanisms triggered by the BRAF inhibitor, as suggested by Mascot identification of markers of autoimmunity like IL7RA as recently reported." (PMID 25437182, 2014). "However, it may cause paradoxical activation of the MAPK/ERK pathway in immune cells without BRAF mutation, which may lead to over activation of the immune system, especially in patients with pre-existing autoimmune conditions." (PMID 38074649, 2023). "Having a preexisting autoimmune condition, receiving systemic steroids for irAEs, or having a BRAF-mutant positive status, did not appear to significantly affect response to pembrolizumab." (PMID 30190931, 2018).
B-cell neoplasm (5 papers, 2017 to 2026). A group of heterogeneous lymphoid tumors generally expressing one or more B-cell antigens or representing malignant transformations of B-lymphocytes. "HCL is a distinct B-cell neoplasm marked by BM infiltration of atypical "hairy" cells, pancytopenia, BM fibrosis, and the BRAF V600E mutation, which is a defining molecular hallmark of the classic form of the disease." (PMID 41789071, 2026). "Conversely, BRAF-V600E is absent in other B-cell neoplasms, including mimickers of HCL that require different treatments (eg, HCL-variant and splenic marginal zone lymphoma)." (PMID 28297625, 2017).
benign thyroid tumors (5 papers, 2018 to 2024). "The BRAF V600E mutation occurred about 45–50% in PTC, 25–30% in ATC, and none in FTC and benign thyroid neoplasm." (PMID 33200656, 2020). "The has-miR-200a-5p as an overexpressed molecule is a sensitive biomarker and could be combined with immunohistochemical markers such as TPO, CD56, Galectin 3, MC, CK19, and BRAF both to detect and to distinguish between PTC and benign thyroid tumor with papillary hyperplasia." (PMID 35186709, 2021).
bile duct cancer (5 papers, 2018 to 2024). "BRAF gene mutation occurs in 5-7% of bile duct carcinomas, with a higher frequency in intrahepatic ones, the most frequent mutation in this case being BRAF 600E." (PMID 38846220, 2024). "The BRAF V600E mutation is found in about 8–10% of CRCs and 3–7% of bile duct cancers." (PMID 35668531, 2022). "The bile-duct cancer cohort included 35 patients treated with the combination of the BRAF inhibitor dabrafenib and the MEK inhibitor trametinib." (PMID 35668531, 2022). "Non-CRC GI malignancies with the highest prevalence of BRAF GOF alterations were bile duct cancers (4.1%) and small intestine cancers (4.0%)." (PMID 38791902, 2024). "This study demonstrates that amongst non-CRC GI cancers, BRAF alterations are most commonly present in bile duct cancers and small intestinal cancers." (PMID 38791902, 2024). "Non-CRC GI malignancies with the highest incidence of BRAF GOF alterations included bile duct cancers (4.1%) and small intestine cancers (4.0%)." (PMID 38791902, 2024).
bone metastasis (5 papers, 2017 to 2025). Transfer of a neoplasm from its primary site to bones. "Among 14 patients who remained alive at the last follow-up, one patient who harbored BRAF V600E mutation had bone metastasis after 53 months of surgery and the other 13 patients were without disease recurrence and/or metastases." (PMID 28423545, 2017). "ECOG score, tumor differentiation, liver metastasis, bone metastasis and primary tumor resection were independent prognostic factors for the OS of BRAF V600E mutant mCRC." (PMID 36912150, 2023).
cardiomyopathy (5 papers, 2017 to 2025). A disease of the heart muscle or myocardium proper. "BRAF inhibitors are associated with a higher risk of cardiomyopathy when combined with MEK inhibitors." (PMID 35269958, 2022). "Considering cardiomyopathy, in a previous study, 27% of patients treated with BRAF/MEKi, represented by D + T in most cases, developed cardiac dysfunction." (PMID 40507236, 2025). "Cardiomyopathy leading to heart failure is a serious adverse effect of treatment with various classes of KIs, including BCR-ABL kinase (e.g., dasatinib, imatinib), c-KIT (ripretinib, imatinib), BRAF/MEK, EGFR, and ALK inhibitors, as well as multitarget KIs used for mRCC treatment." (PMID 35269958, 2022).
cerebellar pilocytic astrocytoma (5 papers, 2012 to 2022). A WHO Grade 1 astrocytoma which arises in the cerebellum. "By far, the most common driver mutation in cerebellar pilocytic astrocytoma is fusion of the BRAF locus with a variety of fusion partners, the most frequent being KIAA1549." (PMID 33206716, 2020). "Taken together, these data suggest this population of ventricular zone progenitor cells as the cell-of-origin for BRAF fusion-positive cerebellar pilocytic astrocytoma." (PMID 33206716, 2020). "Though de-differentiation of a mature cell type induced by BRAF fusion is not excluded, these data raise the intriguing possibility that BRAF fusion-positive cerebellar pilocytic astrocytoma has a prenatal origin, similar to other pediatric cancers." (PMID 33206716, 2020). "The ventricular zone of the cerebellar anlage exhibited significantly more overlap in expression of PA-DR genes than the external granule cell layer, suggesting a ventricular zone origin for BRAF fusion-positive cerebellar pilocytic astrocytoma." (PMID 33206716, 2020). "BRAF mutations are distinct from the KIAA1549:BRAF fusion and other types of BRAF fusions, alterations found frequently especially in cerebellar pilocytic astrocytomas." (PMID 22385786, 2012). "Thus, in conclusion, these data support early ventricular zone progenitor cells on the cusp of their GABA-ergic/astrocytic differentiation point as the cell of origin for BRAF fusion-positive cerebellar pilocytic astrocytoma." (PMID 33206716, 2020). "Taken together, these data support a developmental paradigm operative within BRAF fusion-positive cerebellar pilocytic astrocytoma which recapitulates this early developmental process whereby ventricular zone progenitors differentiate into GABA-ergic and glial lineages." (PMID 33206716, 2020). "It is tempting to speculate that a similar paradigm is true of BRAF fusion-positive cerebellar pilocytic astrocytoma." (PMID 33206716, 2020). "The current findings provide a key first step toward future validation research that may ultimately guide improved and targeted treatment for BRAF fusion-positive cerebellar pilocytic astrocytoma." (PMID 33206716, 2020). "The data presented herein map developmental genes overexpressed in BRAF fusion-positive cerebellar pilocytic astrocytoma to the normal developmental pathway of ventricular zone progenitor cells, suggesting that these cells represent the cell-of-origin for this tumor." (PMID 33206716, 2020).
colorectal polyps (5 papers, 2006 to 2020). "The population-based mutation rates of KRAS and BRAF genes in colorectal polyps within this Chinese patient population were 21.8% and 12.1% respectively." (PMID 26910894, 2016). "Noteworthy, the frequency of BRAF mutations in colorectal polyps is similar to the frequency observed in MSI CRC (28%) (P = 0.9112)." (PMID 18782444, 2008). "Mutations in KRAS, PIK3CA or BRAF occur in 12 (70.6%) of the 17 colorectal polyps." (PMID 18782444, 2008). "We aimed at determine the frequency of KRAS, BRAF and PIK3CA mutations in the process of colorectal tumourigenesis using a series of colorectal polyps and carcinomas." (PMID 18782444, 2008). "In our series of colorectal polyps, we found that mutations in KRAS, PIK3CA or BRAF are mutually exclusive and occur in the majority of these pre-malignant colorectal lesions." (PMID 18782444, 2008). "In contrast, the frequency of BRAF mutations in MSS carcinomas and colorectal polyps is significantly different (P = 0.0191)." (PMID 18782444, 2008). "In our series of colorectal polyps we found the majority (71%) harbour mutations in KRAS (35.3%), PIK3CA (5.9%) or BRAF (29.4%) genes." (PMID 18782444, 2008). "Analyzing the frequency of CIMP in colorectal polyps we have demonstrated that the results obtained are similar to what was described in CRC showing that BRAF mutations are associated with CIMP phenotype in the initial steps of carcinogenesis before malignant transformation." (PMID 18782444, 2008).
diffuse large B-cell lymphoma (5 papers, 2018 to 2024). "MYD88 mutations have been reported to be pathogenetically relevant in some cutaneous diffuse large B-cell lymphomas, leg type, and curiously seem to be mutually exclusive from other cancer-promoting mutations that activate the NF-κB pathway including BRAF, PIK3, or STAT3." (PMID 33333886, 2020). "From these considerations, mouse models, able to mimic human diffuse large B cell lymphoma, were engineered to overexpress murine BRAF Ψ-gene BRAF-rs1 and to follow its putative activity as ceRNA." (PMID 32605220, 2020). "For example, transgenic mice with the full-length murine BRAF pseudogene BRAF-rs1 or its pseudo “CDS” or “3′-UTR” develop an aggressive malignancy resembling human diffuse large B cell lymphoma." (PMID 30071685, 2018). "Indeed, mice engineered to overexpress the full-length murine B-Raf pseudogene Braf-rs1 develop an aggressive malignancy resembling human diffuse large B cell lymphoma by ceRNA mechanism that elevates BRAF expression." (PMID 32341372, 2020).
endometriosis (5 papers, 2018 to 2025). The growth of functional endometrial tissue in anatomic sites outside the uterine body. "The gene encoding serine/threonine kinase (BRAF) is a proto-oncogene that has been identified previously as a candidate target gene in human endometriosis." (PMID 32252625, 2020). "Additionally, increased expression of B-raf proto-oncogene, serine/threonine kinase (BRAF) was also noted in eutopic and ectopic endometrium of women with endometriosis when compared to control endometrium." (PMID 30087267, 2018).
Familial adenomatous polyposis (5 papers, 2015 to 2025). Familial adenomatous polyposis (FAP) is characterized by the development of hundreds to thousands of adenomas in the rectum and colon during the second decade of life. "BRAF p.V600E (50%) or KRAS (p.G12V/D, 40%) mutations were present in 90% of HPs, with one other HP carrying APC p.R213* (rs587781392) which has been reported in the ClinVar database to be associated with familial adenomatous polyposis and APC-associated cancers." (PMID 40757636, 2025). "Here, we used patient-derived organoids (PDOs) derived from a familial adenomatous polyposis (FAP) patient to analyze the response to chemotherapeutic agents targeting EGFR, BRAF and MEK." (PMID 33060766, 2020).
gynecological cancers (5 papers, 2016 to 2024). "Similar results were also reported for AZD5363, although exclusive PIK3CA mutations did not correlate with increased response in another study in breast or gynecological cancer patients where concurrent mutations in KRAS, NRAS, HRAS, or BRAF were excluded." (PMID 31835495, 2019). "BRAF immunohistochemistry or sequencing cannot be used as a proxy for somatic MLH1 hypermethylation in gynecological cancers (grade B)." (PMID 30918358, 2019).
hemorrhage (5 papers, 2017 to 2023). Loss of blood from the vascular compartment to the exterior or into nonvascular body space as a result of rupture or severance of the blood vessels. "Other studies described an increased hemorrhage rate in patients treated with SRS and BRAF inhibitors despite the reported improvement in local control." (PMID 32249551, 2020).
Hyperkeratosis (5 papers, 2015 to 2024). Hyperkeratosis is a histopathological term defining a thickened stratum corneum and may be present in many different skin conditions, with many possible overlaps. "Analysis revealed that therapy with BRAF and MEK inhibitors was associated with lower risk of all-grade hyperkeratosis than BRAF inhibitor alone, with 8.13% of patients from the BRAF and MEK inhibitors therapy group developing hyperkeratosis compared with 29.83% of the BRAF inhibitor alone group." (PMID 39776585, 2024). "Vemurafenib, the first introduced BRAF inhibitor drug, was associated with a multitude of cAEs, including rash, increased sensitivity to ultraviolet rays, palmar-plantar erythro-dysesthesia (“hand-foot syndrome”), alopecia, itching, keratosis pilaris-like manifestations and hyperkeratosis." (PMID 33808846, 2021). "A careful oral evaluation is not routinely performed in treated patients and consequently the real incidence of oral BRAF induced mucosal hyperkeratosis remains unknown." (PMID 33808846, 2021). "The described patient had a BRAF mutation-positive metastatic papillary thyroid carcinoma and was treated with a BRAF inhibitor on a clinical trial and developed Dupuytren’s contractures of both hands, palmar hyperkeratosis, a keratosis pilaris-like eruption and erythema nodosum." (PMID 26152183, 2015).
hypertrophic cardiomyopathy (5 papers, 2016 to 2025). A condition in which the myocardium is hypertrophied without an obvious cause. "Patients with BRAF variants often exhibit a high prevalence of ectodermal anomalies, neurodevelopmental delay, and cardiac defects, including hypertrophic cardiomyopathy." (PMID 40332000, 2025). "BRAF encodes a serine/threonine kinase that is a direct effector of Ras, and the T599R activating BRAF mutation is associated with aberrant activation of the Ras/MAPK pathway, resulting in a hypertrophic cardiomyopathy (HCM) phenotype." (PMID 38165745, 2024). "Finally, it can be theorized that combined BRAF and MEK inhibition can cause a morphological picture of an apical type of hypertrophic cardiomyopathy in a subgroup of treated patients." (PMID 39583362, 2024).
hypothyroidism (5 papers, 2015 to 2024). Abnormally low levels of thyroid hormone. "The enlargement of thyroid glands in some of our BRAF(+) mice, suggesting hypothyroidism, is in concordance with existing data." (PMID 26625260, 2015). "The ideal model would consist also of control group with wild-type BRAF transgene and would include the intervention to overcome the BRAF-induced hypothyroidism and document euthyreosis by TSH serum levels measurements in all animals." (PMID 26625260, 2015). "We also note that, while NRS, BRAF-NRS, and FAS have been validated in some disorders, currently there is no single fatigue behavioral instrument that has been validated in both hypothyroidism and CFS." (PMID 38505756, 2024). "Tg-BRAF mice show increase TSH levels due to hypothyroidism, and this effect could explain the nuclear expression of FAM83F in Tg-BRAF PTC samples." (PMID 30881348, 2019).
invasive breast carcinoma (5 papers, 2014 to 2024). A carcinoma that infiltrates the breast parenchyma. "Using an unbiased approach, we found that mutations in BRAF, EGFR and KIT are significantly more common in this heavily treated population when compared with the cohort of invasive breast carcinoma patients in The Cancer Genome Atlas (TCGA)." (PMID 28247034, 2017).
nasopharyngeal carcinoma (5 papers, 2019 to 2022). A carcinoma arising from the nasopharyngeal epithelium. "The prognostic value of programmed death-ligand 1 (PD-L1) and BRAF expression in nasopharyngeal carcinoma (NPC) is not well-defined." (PMID 31664962, 2019).
neuroendocrine tumors (5 papers, 2016 to 2025). "The patient with BRAF V600E mutation was 52 years old and had a metastatic grade 1 neuroendocrine tumor." (PMID 26684240, 2016). "Only a small number of published studies have described mutations in BRAF in neuroendocrine tumors." (PMID 31158244, 2019).
neurofibromatosis (5 papers, 2017 to 2024). A hereditary neoplastic syndrome in which tumors grow in the nervous system. "Seven LGGs had BRAF-mutation, six had BRAF-fusion, and two were empirically treated (one neurofibromatosis and one DLGNT)." (PMID 39399174, 2024).
pancreatic NETs (5 papers, 2016 to 2024). "The clinical significance of BRAF alterations in well-differentiated (WD) metastatic pancreatic neuroendocrine tumor (panNET) is unknown, but BRAF-mutated panNET could represent a subset characterized by an identifiable and clinically actionable driver." (PMID 31158244, 2019). "Consistent with our previous report on pancreatic NETs, patients with rectal NETs frequently exhibited double LOH, which differed from matually exclusive pattern between K-RAS and BRAF mutations in colorectal cancer." (PMID 30787304, 2019). "Dual BRAF/MEK inhibition with dabrafenib/trametinib therapy led to a significant and durable partial response in a treatment-refractory patient with unresectable, metastatic well-differentiated pancreatic neuroendocrine tumor grade 3." (PMID 38814411, 2024).
pediatric cancers (5 papers, 2016 to 2022). "Because some genes with frequent mutations in pediatric cancers such as BRAF and H3F3A also showed higher mutation rates in AYAs than in OAs, we tested if their increased mutation rates were an extension of their frequent mutations in pediatric cancer." (PMID 36433963, 2022). "Abnormalities in six genes (NRAS, ABL1, JAK2, KIT, ALK and BRAF) were common in childhood cancers as well as adult cancers, for which at least one approved drug could be a potentially actionable drug." (PMID 33051474, 2020). "Finally, dual‐color, break‐apart BRAF probe will help us to detect the presence of any fusion within the BRAF gene in sporadic pediatric cancer." (PMID 27037835, 2016). "Personalized medicine in childhood cancer aims for the identification of actionable alterations and some promising molecular drug targets are already being translated into clinical applications (e.g., ALK, NTRK, MET, BRAF)." (PMID 35159116, 2022). "Although further studies increasing the number of CSF derived ctDNA are required, we found serum as the most promising alternative rather than plasma for BRAF V600E by dPCR detection in liquid biopsy from CNS pediatric cancers." (PMID 31881643, 2019).
pheochromocytoma (5 papers, 2013 to 2025). "Furthermore, an activating mutation in the BRAF gene was recently found in one sample of pheochromocytoma." (PMID 28187001, 2017). "Somatic mutations of BRAF and RAD54B were detected in Langerhans cells and EPAS1 in pheochromocytoma." (PMID 40290304, 2025). "BRAF expression was up-regulated in pheochromocytoma and paraganglioma (PCPG) and CHOL, down-regulated in testicular germ cell tumors (TGCT) and uterine carcinosarcoma (UCS)." (PMID 35910024, 2022). "Mutations in some genes have been found only in single patients or families (e.g., MEN1, EGLN1, EGLN2, MDH2, IDH1, BAP1, BRAF); therefore, their role in the formation of paragangliomas/pheochromocytomas cannot be reliably confirmed." (PMID 28187001, 2017).